LINC01629 (long independently transcribed non-coding RNA 1629)
Synonyms: linc-KIAA1737-2
Gene: Long non-coding RNA gene on chromosome 14 (76,959,552 to 76,970,795, forward strand). Ensembl gene ENSG00000258602.
Diseases named in the same sentence as LINC01629 in open-access papers:
LINC01629 is named in the same sentence as 1 disease in open-access papers, as found by Europe PMC text mining. Sharing a sentence is not in itself a finding about the gene and the disease.
LINC01629 shares sentences with these, for which no sentence is quoted: tumor (1 paper).